RNU6-141P (RNA, U6 small nuclear 141, pseudogene)
Gene: Small nuclear RNA gene on chromosome 6 (20,452,369 to 20,452,473, reverse strand). Ensembl gene ENSG00000222431.
Homologues: Orthologues: chimpanzee U6 (97% identical), macaque U6 (91% identical). Paralogues in human: RNU6-379P (85% identical), RNU6-1044P (84% identical), RNU6-1243P (84% identical), RNU6-1094P (83% identical), RNU6-11P (83% identical), RNU6-1251P (83% identical), RNU6-1331P (83% identical), RNU6-175P (83% identical), RNU6-242P (83% identical), RNU6-34P (83% identical), RNU6-37P (83% identical), RNU6-41P (83% identical), and 1285 more.